PCAT6 (prostate cancer associated transcript 6)
Diseases named in the same sentence as PCAT6 in open-access papers (continued):
Sharing a sentence is not in itself a finding about the gene and the disease.
lung adenocarcinoma (6 papers, 2017 to 2024). A carcinoma that arises from the lung and is characterized by the presence of malignant glandular epithelial cells. "We found that lncRNA PCAT6 expression was elevated, which was also validated in lung adenocarcinoma tissues and cell lines." (PMID 36787056, 2023). "Based on pathway crosstalk analysis, PCAT6 has been identified as a hub lncRNA that is closely related to the clinical features of lung adenocarcinoma." (PMID 33634115, 2021). "ROC curves constructed using plasma PCAT6 levels in patients with lung adenocarcinoma and lung squamous cell carcinoma yielded areas under the curve (AUC) of 0.9213 (sensitivity 87.67%; specificity 97.44%) and 0.9583 (sensitivity 94.12%; specificity 100%), respectively." (PMID 38606479, 2024). "For example, METTL3 increased m6A modification of PCAT6, resulting in PCAT6 upregulation in an IGF2BP2-dependent manner; LCAT3 stability was significantly increased in a METTL3-dependent manner in lung adenocarcinomas, thereby activating MYC transcription via FUBP1." (PMID 35037556, 2022).
osteosarcoma (6 papers, 2020 to 2024). A usually aggressive malignant bone-forming mesenchymal neoplasm, predominantly affecting adolescents and young adults. "For instance, lncRNA prostate cancer associated transcript 6 (PCAT6) promote the progression of osteosarcoma through function as ceRNA of miR-185-5p." (PMID 33117693, 2020). "Several PCAT6-associated pathways have been reported in osteosarcoma." (PMID 34327141, 2021). "Overexpression of lncRNA PCAT6 significantly increases the proliferation, migration, and invasion abilities of osteosarcoma cells." (PMID 39062505, 2024). "PCAT6 was upregulated in osteosarcoma tissues compared with adjacent normal tissues, as seen by qRT-PCR assays." (PMID 34327141, 2021). "High expression of PCAT6 was positively correlated with advanced stage and metastasis status of osteosarcoma." (PMID 34327141, 2021). "PCAT6 can promote osteosarcoma cell proliferation, migration, and invasion." (PMID 34327141, 2021). "In addition, PCAT6 has been shown to be aberrantly expressed in osteosarcoma, ovarian, lung, colorectal, cervical, and pancreatic ductal cancers, thereby suggesting that PCAT6 is associated with the clinicopathological characteristics and prognosis of tumors." (PMID 34247605, 2021). "Mechanistic studies revealed that PCAT6 can increase ZEB1 levels by sponging endogenous miR-143-3p, and the upregulation of ZEB1 can aggravate the malignant phenotype of osteosarcoma cells." (PMID 34327141, 2021). "PCAT6 increases ZEB1 levels by sponging endogenous miR-143-3p, which supports the malignant phenotype of osteosarcoma cells." (PMID 34327141, 2021). "In addition, PCAT6 mediates the same signaling pathways in some tumors, like how PCAT6 can mediate the Wnt/β-catenin pathway in GIST and osteosarcoma." (PMID 34327141, 2021).
colorectal cancer (5 papers, 2019 to 2024). A primary or metastatic malignant neoplasm that affects the colon or rectum. "Our study identified PCAT6 as a potential biomarker for the recurrence and metastasis of colorectal cancer." (PMID 38606479, 2024). "Our study revealed the significant role of PCAT6 in the progression of colorectal cancer and elucidated the specific mechanism by which PCAT6 promotes metastasis in colorectal cancer." (PMID 38606479, 2024). "PCAT6 induced colorectal cancer resistance to 5‐fluorouracil‐based chemotherapy by sponging miR‐204 and activating the HMGA2 pathway." (PMID 34185427, 2021). "Huanget al. reported that PCAT6 could inhibit apoptosis, and Wuet al. reported that PCAT6 plays an important role in regulating chemoresistance in colorectal cancer." (PMID 38606479, 2024).
hepatocellular carcinoma (5 papers, 2019 to 2025). A malignant tumor that arises from hepatocytes. "Knockdown of PCAT6 could inhibit cell proliferation and migration in hepatocellular carcinoma (LIHC) cells." (PMID 30968586, 2019). "Publicly available RNA-seq data of 374 HCC patients and 50 adjacent tissues from the TCGA-liver hepatocellular carcinoma (LIHC) dataset, combined with qRT-PCR data from 29 pairs of HCC tissues, revealed that PCAT6 expression was markedly upregulated in HCC tissues compared with adjacent tissues." (PMID 34327141, 2021).
ovarian carcinoma (5 papers, 2020 to 2024). A malignant neoplasm originating from the surface ovarian epithelium. "Until now, the details of the underlying mechanism of PCAT6 in ovarian cancer have remained elusive." (PMID 33634115, 2021). "Loss-of-function and gain-of-function assays showed that PCAT6 induces cell proliferation, invasion and migration in ovarian cancer cells." (PMID 33634115, 2021). "In our research, we found that PCAT6 expression is upregulated in ovarian cancer tissues and is associated with clinical stage and patient survival." (PMID 33634115, 2021). "Despite these findings, little is known about the underlying mechanisms of PCAT6 in ovarian cancer carcinogenesis." (PMID 33634115, 2021). "Furthermore, other underlying mechanisms of PCAT6 in ovarian cancer development should be explored." (PMID 33634115, 2021). "In ovarian cancer, PCAT6 potentially promotes cell proliferation, migration, and invasion by inhibiting PTEN." (PMID 34327141, 2021). "Taken together, these findings indicate that the lncRNA PCAT6 plays an oncogenic role in the development of ovarian cancer." (PMID 33634115, 2021). "Based on these results, we infer that PCAT6 plays oncogenic roles in the malignancy of ovarian cancer by sponging miR-143-3p and reducing its activity, thus increasing TAK1 expression." (PMID 33634115, 2021). "First, the SKOV3 and A2780 cell lines were used for both PCAT6 overexpression and knockdown experiments to evaluate the malignant phenotype of ovarian cancer." (PMID 33634115, 2021). "In the GSE137238 dataset, we first observed significant upregulation of PCAT6 expression in primary ovarian cancer patient samples compared with matched normal fallopian tube samples (P = 0.015)." (PMID 33634115, 2021). "We verified the expression of PCAT6 in ovarian cancer and normal ovarian tissues using GEPIA and confirmed that PCAT6 was significantly overexpressed in ovarian cancer tissues (P < 0.05)." (PMID 33634115, 2021). "In ovarian cancer, PCAT6 promoted the development and progression of ovarian cancer by regulating PTEN." (PMID 34247605, 2021). "Functional experiments demonstrated that PCAT6 promoted ovarian cancer cell proliferation, migration and invasion." (PMID 33634115, 2021). "Together, our findings indicate that PCAT6 is a potential ovarian cancer diagnostic and prognostic biomarker and that the PCAT6-miR-143-3p-TAK1 axis participates in proliferation, migration and invasion in ovarian cancer." (PMID 33634115, 2021). "One recent study has shown that PCAT6 might promote the malignancy of ovarian cancer cells by inhibiting PTEN." (PMID 33634115, 2021). "Moreover, PCAT6 promoted malignancy of ovarian cancer via its interaction with miR-143-3p and effects on TAK1 expression." (PMID 33634115, 2021). "The key findings of our present study are that PCAT6 is significantly elevated in ovarian cancer tissues and that this elevation is associated with advanced TNM stage and poor prognosis, indicating that PCAT6 is a potential diagnostic and prognostic marker for ovarian cancer." (PMID 33634115, 2021). "All these findings indicate that PCAT6 might affect the behaviors of ovarian cancer cells by regulating TAK1." (PMID 33634115, 2021). "To better understand the function of PCAT6 in ovarian cancer development, we then examined whether knockdown or overexpression of PCAT6 affects the proliferation, migration and invasion of ovarian cancer cells." (PMID 33634115, 2021). "miR-143-3p was negatively regulated by PCAT6 in ovarian cancer cells." (PMID 33634115, 2021). "To explore whether PCAT6 can act as a ceRNA in ovarian cancer, we combined small-RNA sequencing, bioinformatic analysis and dual-luciferase reporter assays and verified that miR-143-3p was a direct target of PCAT6." (PMID 33634115, 2021). "PCAT6 can promote ovarian cancer occurrence and progression by inhibiting PTEN." (PMID 33552977, 2020).
ovarian carcinoma (continued). "Further functional experiments in two cell lines demonstrated that knockdown of PCAT6 suppresses cell proliferation, migration and invasion, while overexpression of PCAT6 produces the opposite results, indicating that PCAT6 exerts an oncogenic function in ovarian cancer development." (PMID 33634115, 2021). "Considering that PCAT6 acts as a ceRNA to regulate TAK1 expression by binding to miR-143-3p, we performed rescue assays to validate whether miR-143-3p is involved in the PCAT6-mediated promotion of proliferation, migration, and invasion in ovarian cancer cells." (PMID 33634115, 2021). "Therefore, we propose that PCAT6 may play a major role in ovarian cancer cells by sponging miR-143-3p during ovarian cancer progression." (PMID 33634115, 2021). "In the present study, we found that PCAT6 was upregulated in ovarian cancer tissues and that elevated expression of PCAT6 was correlated with reduced OS, PFS and PPS in ovarian cancer patients." (PMID 33634115, 2021). "The prognostic value of PCAT6 in ovarian cancer patients was assessed, and Kaplan–Meier Plotter analysis demonstrated that high expression of PCAT6 was correlated with poor OS, PFS and PPS in ovarian cancer patients (all P < 0.05)." (PMID 33634115, 2021). "Furthermore, among patients with different stages of ovarian cancer based on the GSE143897 dataset, the expression of PCAT6 significantly increased from stage II/III to stage IV (P = 0.02)." (PMID 33634115, 2021). "Additionally, the expression of miR-143-3p was increased after PCAT6 was inhibited, while it was decreased after PCAT6 was overexpressed in both SKOV3 and A2780 ovarian cancer cells." (PMID 33634115, 2021). "Additionally, we demonstrate that the oncogenic activity of PCAT6 is attributable to the ceRNA regulatory network of the PCAT6-miR-143-3p-TAK1 axis, which is a potential therapeutic target for ovarian cancer." (PMID 33634115, 2021).
triple-negative breast carcinoma (4 papers, 2020 to 2022). An invasive breast carcinoma which is negative for expression of estrogen receptor (ER), progesterone receptor (PR), and human epidermal growth factor receptor 2 (HER2). "In triple-negative breast cancer, PCAT6 inhibition increases radiosensitivity of cancer cells through ceRNA pattern to regulating miR-185/TPD52 axis." (PMID 34277403, 2021).
esophageal squamous cell carcinoma (2 papers, 2022 to 2023). Esophageal squamous cell carcinoma (ESCC) is a type of esophageal carcinoma (EC) that can affect any part of the esophagus, but is usually located in the upper or middle third. "In Eca-109 and Kyse-30 cells, the knockdown of PCAT6 promoted apoptosis in esophageal squamous cell carcinoma." (PMID 37373132, 2023).
lung squamous cell carcinoma (2 papers, 2021 to 2024). "The results revealed that PCAT6 was up-regulated in most cancers, including Cholangio carcinoma (CHOL), lung squamous cell carcinoma (LUSC), ovarian serous cystadenocarcinoma (OV), and thymoma (THYM)." (PMID 34247605, 2021).
lymph node metastasis (2 papers, 2021 to 2024). "Cox regression analysis indicated that PCAT6 expression is significantly correlated with lymph node metastasis (P=0.006), distant metastasis (P=0.004), and TNM stage (P=0.001)." (PMID 38606479, 2024). "Single-factor Cox regression model analysis revealed that the depth of invasion, lymph node metastasis, distant metastasis, and PCAT6 expression are prognostic factors in patients with CRC." (PMID 38606479, 2024). "Moreover, after excluding missing values, the results of the univariate Cox regression model analysis indicated that the depth of invasion, lymph node metastasis, distant metastasis, and PCAT6 expression are prognostic factors in patients with CRC." (PMID 38606479, 2024).
breast tumors (1 paper, 2024). "Thus, PCAT6 was involved in regulating the nuclear export of m6A‐tagged mRNA in hypoxic BC cells to facilitate the malignant progression of breast tumors." (PMID 38626369, 2024).
glioblastoma (1 paper, 2021). The most malignant astrocytic tumor (WHO grade IV). "In glioblastoma multiforme (GBM), PCAT6 could upregulate IGF2BP1 expression by acting as a ceRNA against miR-513, causing a PCAT6/miR-513/IGF2BP1 positive feedback loop that facilitates GBM progression." (PMID 34327141, 2021).
sarcoma (1 paper, 2021). A usually aggressive malignant neoplasm of the soft tissue or bone. "Experts have used various methods to verify that PCAT6 is highly expressed in a variety of carcinoma and sarcoma tissues and cells." (PMID 34327141, 2021).
serous ovarian cancer (1 paper, 2021). "Then, we found that PCAT6 levels were higher in serous ovarian cancer tissues and ascites than in benign tissues based on the GSE143897 dataset (P = 0.009)." (PMID 33634115, 2021).
squamous cell carcinoma (1 paper, 2020). A carcinoma arising from squamous epithelial cells. "On the other hand, the expression of LINC00673 (p = 6.42 × 10–30), PCAT6 (p = 1.01 × 10–7), NUTM2A-AS1 (p = 3.69 × 10–5) and LINC01929 (p = 3.26 × 10–6) was significantly higher in squamous cell carcinomas than in adenocarcinomas." (PMID 32020063, 2020).
cancer (33 papers, 2019 to 2024). A tumor composed of atypical neoplastic, often pleomorphic cells that invade other tissues. "Another lncRNA expressed at advanced stages of OC patients, which correlated with poor overall survival, progression-free survival, and post-progression survival according to human cancer datasets, was the prostate cancer-associated transcript 6 (PCAT6)." (PMID 38571882, 2024). "LncRNA prostate cancer-associated transcript 6 (PCAT6) has been reported as an oncogene in many cancers." (PMID 36810034, 2023). "By regulating the expression of PCAT6 in GC, cancer-associated protein levels will be affected via signaling pathways." (PMID 34327141, 2021). "OS and DFS were shorter in the PCAT6 high expression group compared to the PCAT6 low expression group, thereby confirming that PCAT6 overexpression was associated with poor OS in various human cancers (P < 0.0001)." (PMID 34247605, 2021). "Prostate cancer-associated transcript 6 (PCAT6) is a member of a group of 121 lncRNAs associated with prostate cancer." (PMID 34771549, 2021). "Prostate cancer-associated transcript 6 (PCAT6) is a novel lncRNA that extensively promotes multiple cancer progression." (PMID 34885209, 2021). "The results revealed that PCAT6 expression was significantly higher in eight cancers, and that high PCAT6 expression strongly associated with poor patient prognosis." (PMID 34247605, 2021). "This review aims to summarize the abnormal expression and subcellular localization of PCAT6, and to further understand the underlying mechanisms, and its diagnostic or prognostic values in multiple human cancers." (PMID 34885209, 2021). "Increasing numbers of studies have illustrated that high expression levels of PCAT6 are associated with many human cancers." (PMID 34885209, 2021). "LncRNA prostate cancer-associated transcript 6 (PCAT6) has been reported to be dysregulated in several cancers and is associated with tumor progression." (PMID 34247605, 2021). "LncRNA prostate cancer‐associated transcript 6 (PCAT6) acts as an oncogene in many cancers; herein, PCAT6 expression was abnormally upregulated in CRC tissues and cell lines, suggesting its potential role in CRC." (PMID 30938104, 2019). "Using LncRNA microarrays, PCAT6 was further confirmed to be the most up-regulated lncRNA expressed in cancer tissues, and it was revealed to be significantly associated with prostate cancer metastasis, induced-colony formation, and the proliferation of keratin-forming cells in prostate cells." (PMID 34247605, 2021). "Hence, PCAT6, as a promising diagnostic biomarker, may be a checkpoint target for precision therapy in human cancers." (PMID 34885209, 2021). "PCAT6 was first discovered in 2013 through a comprehensive genomic analysis of different cancer tissues." (PMID 38606479, 2024). "According to a meta-analysis involving 937 patients and 8 cancer types, high PCAT6 expression was significantly negatively correlated with overall, progression-free, and disease-free survival, as well as TNM stage and metastasis." (PMID 38606479, 2024). "Although the roles of lncRNA PCAT6 are studied extensively in various cancers, their role in LSCC is not well understood." (PMID 38950346, 2024). "Mechanism research has shown that PCAT6 promotes cancer growth by sponging tumor suppressor miR-139-3p that downregulates Bcl-2 and BRD4 while induces Bax and Cleaved caspase-3." (PMID 38204968, 2023). "Higher expression levels of PCAT6 were identified in a variety of cancers through pan-cancer analysis." (PMID 35069911, 2022). "Next, 1062 patients with nine cancer types were divided into two groups based on median levels of PCAT6 expression." (PMID 34247605, 2021). "The aim of the present study was to elucidate the relationship between PCAT6 and cancer, clinical case characteristics, and prognosis." (PMID 34247605, 2021). "To further investigate PCAT6 expression in various cancers, we used two public databases to determine PCAT6 expression in various cancers." (PMID 34247605, 2021).